CHRNB3 (cholinergic receptor nicotinic beta 3 subunit)
Description:
Component of neuronal acetylcholine receptors (nAChRs) that function as pentameric, ligand-gated cation channels with high calcium permeability among other activities. nAChRs are excitatory neurotrasnmitter receptors formed by a collection of nAChR subunits known to mediate synaptic transmission in the nervous system and the neuromuscular junction. Each nAchR subunit confers differential attributes to channel properties, including activation, deactivation and desensitization kinetics, pH sensitivity, cation permeability, and binding to allosteric modulators. Has an accessory rather than functional role and is only able to form functional nAChRs when co-assembled with another beta subunit. Participates in pentameric assemblies along with CHRNA3, CHRNA4, CHRNA6, CHRNB2 and CHRNB4. Modulates receptor assembly and increases receptor sensitivity to nicotine when associated with CHRNB2, CHRNA4 and/or CHRNA6 as well as CHRNA3 and CHRNB4. Seems to play a role in nicotine addiction.
Tractability: Small molecule: a structure with a bound ligand is known; a high-quality ligand is known; it belongs to a druggable protein family. Antibody: its Gene Ontology location is reachable by antibodies, with high confidence; UniProt places it where antibodies can reach, with medium confidence; UniProt predicts a signal peptide or a membrane-spanning region. PROTAC: a small molecule that binds it is known.
Gene: Protein-coding gene on chromosome 8 (42,697,366 to 42,737,407, forward strand). Ensembl gene ENSG00000147432.
Subcellular location: Synaptic cell membrane; Cell membrane
Pathways (Reactome):
Neuronal System: Highly calcium permeable nicotinic acetylcholine receptors; Highly calcium permeable postsynaptic nicotinic acetylcholine receptors
Gene Ontology:
Molecular function: acetylcholine-gated monoatomic cation-selective channel activity; acetylcholine receptor activity; channel activity; neurotransmitter receptor activity; extracellular ligand-gated monoatomic ion channel activity; monoatomic ion channel activity; transmembrane signaling receptor activity
Biological process: acetylcholine receptor signaling pathway; calcium ion transport; membrane depolarization; monoatomic ion transmembrane transport; neuromuscular synaptic transmission; presynaptic modulation of chemical synaptic transmission; response to nicotine; signal transduction; synaptic transmission, cholinergic; chemical synaptic transmission, postsynaptic; excitatory postsynaptic potential; monoatomic ion transport; regulation of postsynaptic membrane potential
Cellular component: acetylcholine-gated channel complex; membrane; neuron projection; plasma membrane; synapse; synaptic membrane; dopaminergic synapse; postsynaptic membrane; presynapse
Genetic constraint (gnomAD): Loss-of-function variants: 27 observed, 34.94 expected, observed/expected ratio (o/e) 0.77, 90% interval 0.57 to 1.07. The upper end of that interval is the gene's LOEUF score, 1.07, which puts it in group 4 of 6, group 1 being the genes least tolerant of losing a copy. Missense variants: 440 observed, 516.26 expected, observed/expected ratio (o/e) 0.85, 90% interval 0.79 to 0.92. Synonymous variants: 189 observed, 200.26 expected, observed/expected ratio (o/e) 0.94, 90% interval 0.84 to 1.07.
Homologues: Orthologues: chimpanzee CHRNB3 (100% identical), macaque CHRNB3 (98% identical), rabbit CHRNB3 (92% identical), dog CHRNB3 (90% identical), pig CHRNB3 (90% identical), guinea pig CHRNB3 (90% identical), rat Chrnb3 (87% identical), mouse Chrnb3 (86% identical), tropical clawed frog chrnb3 (82% identical), zebrafish chrnb3a (76% identical), zebrafish chrnb3b (74% identical). Paralogues in human: CHRNA5 (65% identical), CHRNA2 (53% identical), CHRNA4 (52% identical), CHRNA3 (48% identical), CHRNA6 (47% identical), CHRNA1 (42% identical), CHRNB4 (42% identical), CHRNB2 (41% identical), CHRNB1 (36% identical), CHRND (36% identical), CHRNA7 (35% identical), CHRNA10 (32% identical), and 33 more.
Diseases named in the same sentence as CHRNB3 in open-access papers:
CHRNB3 is named in the same sentence as 11 diseases in open-access papers, as found by Europe PMC text mining. Sharing a sentence is not in itself a finding about the gene and the disease. The quoted sentences say what the papers report.
nicotine dependence (19 papers, 2008 to 2026). Physical and psychological dependence on nicotine. "The other nicotine receptor gene CHRNB3-CHRNA6 was first identified with genome-wide significance in an isolated population for associations with nicotine dependence and nicotine use." (PMID 30016313, 2018). "Genetic association for the risk of developing nicotine dependence was recently confirmed for one polymorphism within the CHRNB3–CHRNA6 gene cluster." (PMID 29910731, 2018). "Many other GWASs also showed an association of CHRNB3–CHRNA6 with nicotine addiction, which was replicated by many other candidate gene studies." (PMID 27827986, 2016). "Single nucleotide polymorphisms (SNPs) in CHRNB3 were associated with nicotine dependence and cigarettes smoked per day." (PMID 25233467, 2014). "Genome-wide association studies have identified single nucleotide polymorphisms (SNPs) as risk factors for nicotine dependence and lung cancer in genes encoding nAChR subunits (CHRNB3-CHRNA6 and CHRNB4-CHRNA3-CHRNA5 clusters), and in nicotine-metabolizing enzymes (CYP2A6 and CYP2B6)." (PMID 26623516, 2015). "A wider survey of nAChR gene variants in a case-control study for nicotine dependence found evidence for nominally significant associations in CHRNA7, CHRNA9, CHRNA5 and CHRNB3 in young Israeli women." (PMID 18618000, 2008). "Hartz and colleagues, focusing on the nicotinic receptor subunit genes associated with nicotine dependence (CHRNA5/CHRNA3/CHRNB4 on chromosome 15q25 and CHRNB3/CHRNA6 on chromosome 8p11) investigated the relationship between nicotine dependence and bipolar disorder." (PMID 35893041, 2022). "We previously undertook pooled sequencing of the coding regions and flanking sequence of the CHRNA5, CHRNA3, CHRNB4, CHRNA6 and CHRNB3 genes and found that rare missense variants at conserved residues in CHRNB4 are associated with reduced risk of nicotine dependence among African Americans." (PMID 24804708, 2014). "Therefore, the objective was to characterize the mediation effects of nicotine dependence on the relationship between genetic variants in the five nicotinic receptor genes (CHRNA5/A3/B4, CHRNB3, and CHRNA6) and lung ADC risk among ever smokers." (PMID 25233467, 2014). "CHRNB3 is a kind of nicotinic acetylcholine receptor, and a study among Caucasian smokers involving 661 lung ADC cases and 1347 controls found that two CHRNA3 SNPs (rs1051730 and rs12914385) associated with ADC risk had significant indirect effects on lung ADC risk through nicotine dependence." (PMID 35499292, 2022). "Such phenotype differences have similarly been observed for the established CHRNB3 region, whereby genome-wide significant variants were identified when using FTND-defined nicotine dependence but not when using CPD." (PMID 26440539, 2015).
dependence (2 papers, 2020 to 2022). "One such candidate is the CHRNB3-CHRNA6 gene cluster, which has been associated with substance dependence especially in Europeans (see Discussion)." (PMID 32555579, 2020). "The authors reported two main findings: the first is that bipolar disorder does not influence and modify the association between nicotine dependence and nicotinic receptor subunit genes, and the second main finding is that variants in CHRNB3/CHRNA6 are independently associated with bipolar disorder." (PMID 35893041, 2022).
lung carcinoma (2 papers, 2014 to 2015). "Based on the National Human Genome Research Institute (NHGRI) GWAS Catalog, SNPs in CHRNA5/A3/B4 are associated with overall lung cancer, lung ADC, and smoking; SNPs in CHRNB3 are associated with cigarettes smoked per day." (PMID 25233467, 2014).
alcohol addiction (1 paper, 2024). "In females, single variants in AANAT (OR 2.83, p < 0.01) and CHRNB3 (OR 1.94, p = 0.029) showed a significant risk for alcohol addiction." (PMID 39766481, 2024). "In males, factors exhibiting significant alcohol addiction risk included CHRNB3 (OR 2.35, p < 0.001), DRD4 (OR 1.84, p = 0.018), and CHRNB3_ZBTB20 (OR 3.19, p = 0.018)." (PMID 39766481, 2024). "However, multiple CHRNB3 gene variants showed small but significant associations with alcohol addiction, suggesting that synaptic transmission pathways may play a role in alcohol addiction." (PMID 39766481, 2024).
Alzheimer disease (1 paper, 2015). A progressive, neurodegenerative disease characterized by loss of function and death of nerve cells in several areas of the brain leading to loss of cognitive function such as memory and language. "Among the analysed target genes, nicotinic acetylcholine receptors (CHRNB3, CHRNE, CHRNB1, CHRND) were found, which are targets of drugs against Alzheimer's disease." (PMID 26693857, 2015).
depression (1 paper, 2017). "Here, we demonstrated that the expression levels of cholinergic signaling genes (CHAT, VACHT, CHT, CHRNA3, CHRNB3 and CHRNB4) were down-regulated in a chronic restraint stress (CRS) rat model of depression, in which rats display depression-like behaviors such as anhedonia and mood despair." (PMID 28420875, 2017).
CHRNB3 also shares sentences with these, for which no sentence is quoted: autism (1 paper); bipolar disorder (1); cancer (1); endometriosis (1); tumor (1).